GLI1 (GLI family zinc finger 1)
Diseases named in the same sentence as GLI1 in open-access papers (continued):
Sharing a sentence is not in itself a finding about the gene and the disease.
pancreatic cancer (continued). "In a pancreatic cancer mouse model (Ptf1-Cre; frp-stop-frp-KrasG12D/+; Gli1CreERT), lineage-traced, GLI1-positive cells account for a little less than half of the total myofibroblast population." (PMID 33333727, 2020). "Onishi and colleagues confirmed, using triple staining fluorescence immunohistochemistry of surgically-resected pancreatic cancer tissues, that GLI1 and SMO proteins are partially co-expressed with CAIX, a marker of hypoxia." (PMID 32707920, 2020). "Immunolabeling of Shh-pathway molecules showed that SMO was localized in the cytoplasm and the cell membrane of pancreatic tumor cells and Gli1 was localized in the cytoplasm and the nucleus." (PMID 31417657, 2019). "Authors showed that genetic and pharmacological inhibition of DYRK1B reduces GLI1 expression in a number of cancer types, including human brain and pancreatic cancers, and mouse BCC cells." (PMID 30934935, 2019). "In this regards, Lithium, a clinical mood stabilizer for the treatment of mental disorders, has been reported upregulate both mRNA and protein levels of Itch, thereby accelerating the degradation of GLI1 and leading to pancreatic cancer cell growth inhibition." (PMID 30699938, 2019). "Taken all the data together, we found that acquired gemcitabine resistant pancreatic cancer cells have elevated expression of GLI transcription factors, either GLI1 or GLI2, which is associated with elevated SOX2 expression." (PMID 30382189, 2019). "This is different for many other tumors e.g. for breast and pancreatic cancer, in which HH/GLI1 signaling is connected to migration and invasiveness." (PMID 31867038, 2019). "Expression of SHH/GLI1 was found to be negatively correlated with E-cadherin in oral squamous cell carcinoma and pancreatic cancer patients." (PMID 31036836, 2019). "In orthotopic mouse models using human pancreatic cancer cell lines, we found that Hh target gene Gli1 is up-regulated during pancreatic cancer metastasis." (PMID 30373214, 2018). "In pancreatic cancer cells GLI1 knockdown, perifosine treatment or GANT61 treatment sensitize the cells to gemcitabine." (PMID 30158435, 2018). "We also detected elevated human GLI1 gene expression, indicating activated Hh signaling in the pancreatic cancer cells." (PMID 30373214, 2018). "In mouse models of pancreatic cancer metastasis using human pancreatic cancer cells, we found that Hh target gene Gli1 is up-regulated during pancreatic cancer metastasis." (PMID 30373214, 2018). "It has been shown that oncogenic KRAS can block GLI1 degradation and lead to activation of HH-GLI signaling in pancreatic cancer cells." (PMID 30158435, 2018). "With an increased application of massive parallel sequencing of whole cancer genomes, more mutations in GLI1 and GLI3 have been discovered in breast, colorectal, pancreatic cancers and soft-tissue sarcomas." (PMID 30158435, 2018). "A similar tumor-restraining effect of the Hh/GLI signaling has been observed in pancreatic cancer, in which the increase in the number of GLI1-expressing stromal cells positively correlated with the reduced growth of the tumor." (PMID 29695137, 2018). "Our study demonstrated a significant increase of Shh and Gli1 expression in all the pancreatic cancer cell lines tested, confirming aberrant Shh/Gli1 activity in pancreatic cancers." (PMID 26988754, 2017). "In pancreatic cancer cells it has been shown that lithium treatment reduced the GLI1 mRNA and protein expression." (PMID 28575066, 2017). "Other studies demonstrated that GLI1 transcription factor acts synergistically with activated KRAS to induce metastatic pancreatic cancer." (PMID 26988754, 2017). "Gli1, a transcriptional factor of the Hh signaling pathway, is upregulated in most digestive tumors, including pancreatic cancer, hepatocellular carcinoma and gastric cancer." (PMID 28148279, 2017). "This shows how GLI-1 overexpression promotes an increase in methylation levels of genes such as APC in pancreatic cancer." (PMID 28948003, 2017).
pancreatic cancer (continued). "Shh and Gli1 were upregulated in all pancreatic cancer cell lines such as HPAC, MIAPaCa-2, and PANC-1 compared to normal pancreatic cell line hTERT HPNE." (PMID 26988754, 2017). "Our recent study indicates that lithium inhibits pancreatic cancer cell proliferation through modulating the Hh/Gli signaling pathway by suppressing Gli1." (PMID 29249966, 2017). "Similar to Gli1 regulation by K-Ras in pancreatic cancer, HRAS or NRAS mutation in melanoma stimulates Gli1 nuclear translocation by antagonizing the suppressive effect of SuFu through MEK1/2." (PMID 29163356, 2017). "Our findings suggest that gedunin–induced Gli1 inhibition led to inhibition of pancreatic cancer migration and invasion even in the presence of exogenous rhShh." (PMID 26988754, 2017). "Herein, we demonstrate that gedunin induces anticancer activity on pancreatic cancer by inhibiting proliferation and metastasis through alteration of Shh/GLI1 signaling pathway and also by inducing apoptotic cell death." (PMID 26988754, 2017). "To test the in vivo relevance of these data, we performed xenograft assays with two distinct GLI1-dependent pancreatic cancer cell lines (PANC-1 and L3.6pl)." (PMID 26784250, 2016). "In order to confirm the expression of Hh signaling components, we performed immunofluorescence staining of pancreatic cancer cell lines with anti-SHH or anti-GLI1 antibodies." (PMID 27349387, 2016). "GLI1 also represents a critical determinant of tumor-initiating cancer stem cells in several entities such as glioblastoma, colorectal cancer and pancreatic cancer." (PMID 26784250, 2016). "We have shown that genetic and chemical perturbation of DYRK1B represses the expression of the GLI1 oncogene in a variety of settings, including human brain and pancreatic cancer and murine basal cell carcinoma cells." (PMID 26784250, 2016). "In previous work, others and we have provided evidence for a critical tumorigenic role of GLI1 in pancreatic cancer cells, including reduced formation of tumor-initiating spheroids in vitro and impaired in vivo tumor growth." (PMID 26784250, 2016). "In the present study we show that interfering with DYRK1B dramatically impairs SMO-independent GLI1 expression in RAS mutant pancreatic cancer cells and phenocopies the anti-tumorigenic effect of GLI1 targeting." (PMID 26784250, 2016). "Taken together, these results demonstrate that inhibition of DYRK1B efficiently represses GLI1 expression and reduces the malignant properties of GLI1 dependent cancer cells including pancreatic cancer cells with resistance to SMO inhibitors." (PMID 26784250, 2016). "It has been reported that oncogenic Kras blocks proteasome-mediated GLI1 degradation and consequently leads to the activation of Hh signaling in pancreatic cancer cells." (PMID 26343727, 2015). "Transplantation of GLI1 overexpressing pancreatic cancer cells into nude mice enhanced liver metastasis and intra splenic miniature metastasis." (PMID 26633513, 2015). "In pancreatic cancer cells, GLI1 and GLI2 have been shown to control the expression of MutL homolog 1 (MLH1), a protein necessary for MMR and important for faithful DNA replication." (PMID 26633513, 2015). "In SMO-deleted pancreatic cancer cell line from mouse, TGFβ treatment leads to marked elevation of GLI1 and GLI3, even when GLI2 expression is undetectable." (PMID 26343727, 2015). "A recent study has also reported on the observation of a substantially decreased DNMT1 expression after Gli1 interference in pancreatic cancer cells." (PMID 26317501, 2015). "Analysis of pancreatic cancer samples by immunohistochemistry has revealed an increased expression of GLI1, DNMT1 and DNMT3a in the cancer cells compared to normal cells." (PMID 26633513, 2015). "Inhibition of GLI1 by GANT61 in pancreatic cancer cells has not only reduced its stemness but also sensitized the cells to genistein." (PMID 26633513, 2015).
pancreatic cancer (continued). "In conclusion, these data suggested a model in which Shh-Gli1 signaling pathway promotes metastasis in pancreatic cancer by promoting target genes transcription." (PMID 25072505, 2014). "Since target genes of Gli1 were the key mechanisms of Hh signaling pathway, we attempted to understand its pro-metastatic mechanisms by identifing the targets of Gli1 in pancreatic cancer cells." (PMID 25072505, 2014). "Millset al. examined the role of GLI1 expression in the later stages of PDAC using a mouse model for advanced pancreatic cancer (Millset al., 2014)." (PMID 25352983, 2014). "TGFβ has been shown to promote GLI1 expression in pancreatic cancer cells (Nolan-Stevauxet al., 2009)." (PMID 25352983, 2014). "Embelin inhibited the expression of Gli1 and Gli2 and their down-stream target Cyclin D1 in mouse pancreatic cancer cells." (PMID 24694877, 2014). "On the base of cDNA microarray data, we investigated regulating mechanism of Gli1 to some members of S100A genes family in pancreatic cancer cell lines firstly." (PMID 25072505, 2014). "Because S100A4 as a key EMT moleculer marker was found to be upregulated upon Gli1 in pancreatic cancer cells, we focused on the relationship between Shh-Gli1 signals and S100 genes family." (PMID 25072505, 2014). "The complexity of these findings reflects our incomplete understanding of the precise biological role of HH/GLI1 signaling in pancreatic cancer." (PMID 25352983, 2014). "In this study, we provide a systematic research about the mechanism of Gli1 in a high-metastasis pancreatic cancer cell line, AsPC-1." (PMID 25072505, 2014). "In previous study, we have performed a systematic research about the target gene profiles upon Gli1 in high-metastatic pancreatic cancer cell line through cDNA microarray and found that 5 members of this gene family were upregulated by Gli1." (PMID 25072505, 2014). "Surprisingly, inhibition of PI3K pathway partially increases Gli1 transcriptional activity in pancreatic cancer cells." (PMID 23900341, 2013). "Whereas K-Ras signaling enhances Gli1 transcriptional activity in pancreatic cancer, protein kinase C and PKA negatively regulate Gli1 by affecting its nuclear localization in hepatocellular carcinoma and NIH3T3 cells, respectively." (PMID 23900341, 2013). "Another study demonstrates that Hh signaling activation is a very common event in pancreatic cancer, evidenced by the expression of PTCH1 and GLI1 in seven available pancreatic cancer cell lines and 54 pancreatic cancer surgical specimens." (PMID 23786654, 2013). "Because SHH promotes tumor development predominantly through Gli1, we sought to understand its mechanism by identifying Gli1 targets in pancreatic cancer cells." (PMID 22900095, 2012). "The data demonstrate that the components of SHH signaling pathway, including the ligand (Shh), the signaling molecules (Patched-1, Patched-2 and Smoothened) and effectors (Gli1, and Gli2) are expressed in human pancreatic cancer cell lines and pancreatic CSCs." (PMID 22087285, 2011). "On one hand, Shh-Gli1 signaling acts to inhibit apoptosis of pancreatic cancer cell by directly activating expression of Bcl-2 and indirectly decreasing the levels of Bax and Bak1." (PMID 19736394, 2009). "Annexin V-FITC/PI assay was performed to evaluate apoptosis of cultured pancreatic cancer cells induced by cyclopamine or RNAi for Gli1." (PMID 19736394, 2009). "Overall, these data suggested a model in which Shh-Gli1 signaling controlled surviving state of pancreatic cancer cells by regulating Bcl-2 and IGF family in a parallel manner." (PMID 19736394, 2009). "Additionally, RA reduced the malignancy of pancreatic cancer cells through the negative regulation of the Gli1 signaling pathway." (PMID 39684626, 2024). "Diarylheptanoids can also suppress FOXM1 expression, suppressing Gli1 in pancreatic cancer cells." (PMID 36661515, 2023).
pancreatic cancer (continued). "To investigate whether CSNK1D is required for GLI-driven tumor initiation in vivo, we performed xenograft experiments using GLI1-dependent A673 and GLI1-dependent PANC1 pancreatic cancer cells with concomitant inhibition of CSNK1D." (PMID 34439381, 2021). "However, NDRG1 potentially reduced GLI1, a key driver of pancreatic cancer, to suppress cell migration mediated by pancreatic stellate cells." (PMID 34965023, 2021). "In addition, MAP3K10 enhances pancreatic cancer cells growth probably by increasing GLI1 and GLI2 expression." (PMID 30934935, 2019). "As direct inhibition of Gli expression by siRNA or by the Gli inhibitor Gant61 has been shown to block pancreatic cancer cell growth and survival, Gli1 could be considered a ‘druggable’ therapeutic target in the Hh pathway, downstream of Smo." (PMID 31137846, 2019). "Thus, pancreatic cancer cells express SHH to activate GLI1 in stroma to create a tumor-supportive microenvironment." (PMID 30060755, 2018). "In pancreatic cancer cells, knocking out Gli1 reduces Snail expression." (PMID 29499705, 2018). "Recently, our own group has provided evidence for a critical positive role of DYRK1B rather than DYRK1A in various human cancer entities and shown that genetic and pharmacologic DYRK1B targeting can efficiently eliminate GLI1-dependent tumor-initiating pancreatic cancer cells." (PMID 28122581, 2017). "In human pancreatic cancer cells lithium treatment reduced the GLI1 mRNA and protein expression." (PMID 28575066, 2017). "KRAS cooperates with Gli1 to induce pancreatic cancer in a mouse model." (PMID 29163356, 2017). "Indeed, pancreatic cancer cells, a representative type of cancer exhibiting the Hh signaling-dependent proliferation, express GLI1 predominantly in the cytoplasm, whereas the GLI1 expression is undetectable in normal pancreatic duct epithelium." (PMID 26744317, 2016). "In addition, we analyzed the role of DYRK1B in the regulation of GLI1 expression in pancreatic cancer and Ewing sarcoma cells, where TGFβ/RAS and the EWS-FLI1 oncogene, respectively, control GLI1 expression independent of canonical SMO activity." (PMID 26784250, 2016). "In addition, JIB-04 decreased cell growth and Hh target gene expression in pancreatic cancer cells and GLI1 protein levels in lung carcinoma as well as in rhabdomyosarcoma cells." (PMID 26310823, 2015). "Another transcriptional target for GLI1 in pancreatic cancer was RegIV." (PMID 26633513, 2015). "The components of Sonic Hh signaling pathway, including the ligand (SHh), the signaling molecules (Patched-1, Patched-2 and Smoothened) and effectors (Gli1, and Gli2) are aberrantly expressed in human pancreatic cancer cell lines and pancreatic cancer stem cells." (PMID 26369833, 2015). "Similarly, GLI1-induced MDR has been observed in chemoresistant pancreatic cancer cells and ovarian cancer cells." (PMID 26633513, 2015). "Moreover, the expression level of Gli1 was knocked down moderately by using the RNA interference system, which was more consistent with the actual molecular pathological change of pancreatic cancer than artificial gene knockout." (PMID 25072505, 2014). "DNMT1 and DNMT3a are regulated by GLI1 in pancreatic cancer." (PMID 24822169, 2014). "Moreover, immunohistochemical stainings in human pancreatic tumor samples revealed a significant correlation between Smo, Gli1 and MMP9 expression and the hypoxia marker CA9." (PMID 23880852, 2013). "To determine whether SMO or GLI1 is directly regulated by hypoxia, we exposed pancreatic cancer cells to cyclopamine or GLI1 siRNA in the presence of hypoxia." (PMID 23786654, 2013). "Since we have previously shown the Shh pathway activation in a panel of human pancreatic cell lines, we also sought to examine the effects of SFN on the expression of Shh receptor (Smothened) and effectors (Gli1 and Gli2) by qRT-PCR in pancreatic cancer cells ASPC and PANC-1." (PMID 23029396, 2012).
pancreatic cancer (continued). "Of particular interest, Smoothened-dependent GDC-0449 treatment of pancreatic CSCs markedly inhibited expressions of SHH receptors (Patched-1, Patched-2 and Smoothened) and effectors (Gli1 and Gli2), thereby showing potential for therapeutic application for treatment of pancreatic cancer." (PMID 22087285, 2011). "Our in vivo results lend support to the idea that the primary effect of Hh inhibition in pancreatic cancer treatment is due to the inhibition of Hh pathway activity in the stromal cells, although we also observe a mild initial reduction of GLI1 levels in tumor cells." (PMID 21698280, 2011). "Sonic hedgehog (Shh), Smoothened (Smo), patched and Gli1 were expressed in pancreatic cancer cells." (PMID 19736394, 2009). "Since IGFBP6 and Bcl-2 genes have been proved to be target genes of transcription factor Gli1, we hypothesize that Shh-Gli1 pathway are associated with IGF pathway and Bcl-2 family in pancreatic cancer." (PMID 19736394, 2009). "Moreover, upregulation of IGFBP6 and Bcl-2 following the reactivation of Shh-Gli1 pathway in pancreatic cancer tissues suggest regulation model of Shh-Gli1 pathway to IGFBP6 and Bcl-2 is similar in vivo." (PMID 19736394, 2009). "Finally PCNA, IGFBP6 and Bcl-2 mRNA were upregulated as well as Shh or Gli1 in pancreatic cancer tissues (p < 0.01)." (PMID 19736394, 2009). "We studied the relationship of Shh-Gli1 signaling pathway with proliferation and apoptosis of pancreatic cancer cells and the regulation of transcription factor Gli1 to insulin-like growth factor binding protein 6 (IGFBP6) and Bcl-2 genes at the level of transcription." (PMID 19736394, 2009). "In order to determine whether Hh signaling pathway is activated in pancreatic cancer cell lines, RT-PCR assay was used to examine the expression of Shh, Patched, Smo and Gli1 mRNA in BxPC-3, AsPC-1, Panc-1 and SW1990 cells." (PMID 19736394, 2009). "This might be one of the mechanisms through which Hh signaling pathway maintains cell survival and promotes development of pancreatic cancer, which imply that Shh-Gli1 pathway might be an effective target of treatment for pancreatic cancer." (PMID 19736394, 2009). "Additionally, Gal-1 could enhance the immune cell evasion of pancreatic tumors by hampering T-cell and neutrophil tumor infiltration but whether GLI1 mediated this effect remains to be elucidated." (PMID 34572373, 2021). "As Gal-1 is restricted to the stromal compartment as assessed in pancreatic tumor specimens, Gal-1 could potentially induce GLI1 expression in tumor epithelium cells via paracrine induction, recapitulating the importance of stromal-derived Gal-1 in inducing GLI1 expression in the surrounding tumor." (PMID 34572373, 2021). "Pancreatic cancer with activating mutations in KRAS or BRAF occur frequently, and oncogenic pathways like RAS/RAF/MEK/ERK, the PI3K-AKT-mTOR, and TGFβ signaling converge on the activation of GLI1, promoting cellular proliferation, tumor progression, chemotherapeutic resistance, and early metastasis." (PMID 34113570, 2021). "Several studies have revealed that a crosstalk between hypoxia and HH pathways within pancreatic cancer cells is operated in a ligand-independent manner and that the nuclear accumulation of GLI1 could be triggered via other factors, such as TGF-β, K-ras, and receptor tyrosine kinase (RTK)." (PMID 32707920, 2020). "Indeed, the enhancement in Shh-Gli1 signaling induced migration of pancreatic cancer cells." (PMID 27553089, 2017). "Thus, it seems that S100A4 mediated by abnomal activated Shh-Gli1 signaling pathway could be one of key pro-migration factors in pancreatic cancer cells." (PMID 25072505, 2014). "In addition to TGFβ and KRAS activation, epidermal growth factor receptor (EGFR) signaling, a cascade aberrantly activated in the majority of PDACs, has been demonstrated to play a critical role in HH/GLI1-regulated tumor-initiating pancreatic cancer cells (Eberlet al., 2012)." (PMID 25352983, 2014).